SPARC (secreted protein acidic and cysteine rich)
Diseases named in the same sentence as SPARC in open-access papers (continued):
Sharing a sentence is not in itself a finding about the gene and the disease.
glioma (continued). "In summary, these data demonstrate that SPARC upregulates glioma ECM, collagen I is a constituent of this matrix and SPARC facilitates collagen fibrillogenesis." (PMID 18350569, 2008). "The data demonstrate that SPARC upregulates glioma matrix, collagen I is a constituent of the matrix and SPARC promotes collagen fibrillogenesis." (PMID 18350569, 2008). "SPARC, a matricellular protein that negatively regulates angiogenesis and cell proliferation, but enhances cell deadhesion from matrix, is upregulated in gliomas (Grades II–IV)." (PMID 18350569, 2008). "As SPARC also affects matrix synthesis, and matrix can have a profound affect on vascularity, we determined the effects of SPARC on glioma matrix production." (PMID 18350569, 2008). "The expression of SPARC has been positively correlated with the histological grade of tumour cells in bladder cancer, thyroid cancer, glioma and HCC." (PMID 15558074, 2004). "More importantly, to determine whether ZnPcS can be selectively targeted via SPARC overexpression in the glioma membrane, the selective inflow of ZnPcS was observed using U87-glioma cells that knocked out SPARC protein with CRISPR-Cas9." (PMID 36945032, 2023). "In the CNS, SPARC upregulates glioma matrix by promoting collagen fibrillogenesis." (PMID 36830573, 2023). "The key to this phenomenon is that SPARC is overexpressed in solid cancers, including glioma; thus, it not only triggers tumor growth and angiogenesis, but also increases the absorption of albumin, helping glioma proliferation." (PMID 36945032, 2023). "The overexpression of SPARC provides an uptake pathway for albumin-binding ZnPcS in glioma." (PMID 36945032, 2023). "HSP27 regulates a variety of biological processes in tumor cells and studies have shown that glioma cells express high levels of HSP27 compared to normal cells, which mediates secreted protein acidic and rich in cysteine (SPARC)-induced changes in glioma migration and invasion." (PMID 36639654, 2023). "We determined whether the synthesized ZnPcS could be injected intraperitoneally to pass through the BBB and accurately suppress glioma and whether ZnPcS accurately targets glioma through SPARC in vivo and in vitro." (PMID 36945032, 2023). "Schultz found that inhibition of HSP27 alone, or in combination with pAKT inhibitors, may be an effective treatment to inhibit SPARC-induced glioma cell invasion and survival." (PMID 36639654, 2023). "SPARC expression is elevated in melanoma, glioma, meningioma, kidney cancer, and prostate cancer." (PMID 35211625, 2022). "Similarly, we identified a set of genes in glioma cells that are up-regulated after knockdown of SPARC (secreted protein acidic and cysteine rich) by RNAi." (PMID 32583859, 2020). "Furthermore, they found that suppression of SPARC expression with specific siRNAs in glioma cells decreased tumor cell survival upon the downregulation of FAK and/or ILK expression." (PMID 31897236, 2020). "Since SPARC is known to be a secreted protein, we measured the level of SPARC secreted into the serum-free medium and found it to be highly expressed in and secreted by glioma cells." (PMID 31695779, 2019). "Silencing SPARC removed any residual SPARC production from these gliomas [Suppl." (PMID 31062076, 2019). "This study demonstrates that the prevalent activation of AKT in gliomas increases the ER protein-folding capacity and enables tumor cells to utilize a side effect of RhoA activation: the perturbation of the IRE1α-mediated decay of SPARC mRNA." (PMID 31062076, 2019). "SPARC depletion significantly prolonged survival in several pre-clinical mouse glioma models." (PMID 31062076, 2019). "That exogenous SPARC treatment could increase HSA uptake in glioma cells prompted us to examine if the binding of SPARC to HSA mediated its uptake by tumor cells." (PMID 31695779, 2019).
glioma (continued). "However, these signaling events also lead to deactivation of the ribonuclease IRE1α, which abolishes SPARC mRNA decay and allows glioma cells to secrete SPARC." (PMID 31062076, 2019). "HSA accumulation in U87MG glioma correlates with SPARC expression in vitro and in vivo." (PMID 31695779, 2019). "Tumor accumulation and micro-distribution of HSA in glioma were enhanced by SPARC." (PMID 31695779, 2019). "SPARC enhances HSA accumulation in U87MG glioma and mediates active targeting of HSA in tumors." (PMID 31695779, 2019). "It was evident that SPARC enhanced the HSA targeting effect on U87MG glioma." (PMID 31695779, 2019). "In addition, suppression of SPARC expression decreases Akt, ILK and FAK activation, and SHC/RAF/ERK signaling is also involved in SPARC-mediated invasiveness in glioma." (PMID 28969021, 2017). "In addition miR-145 regulates glioma cell migration by targeting CTGF which downregulates SPARC expression." (PMID 23390502, 2013). "Our finding that SPARC expression is regulated by CTGF and that overexpression of SPARC can abrogate the inhibitory effect of CTGF silencing on cell migration, demonstrates that these two proteins are associated in their effects on glioma cell migration." (PMID 23390502, 2013). "However, although both CTGF and SPARC play a major role in glioma cell migration, interaction of these proteins has not yet been reported." (PMID 23390502, 2013). "As HSP27 and AKT interact to regulate the activity of each other, we determined whether inhibition of HSP27 was better than targeting SPARC as a therapeutic approach to inhibit both SPARC-induced glioma cell invasion and survival." (PMID 22480225, 2012). "Interestingly, SPARC also promotes glioma cell survival under stressful conditions by upregulating AKT activity." (PMID 22480225, 2012). "As the majority of gliomas have high SPARC expression, these data suggest that inhibition of HSP27 ± pAKT may be useful therapeutic approaches." (PMID 22480225, 2012). "Similar results were also found in glioma, SPARC up-regulated the expression of MMP-2 and MMP-9." (PMID 22879971, 2012). "Indeed, we demonstrated that treatment of SPARC-expressing glioma cells with HSP27 siRNA prevented SPARC-induced migration and invasion." (PMID 22480225, 2012). "In glioma, we previously demonstrated that SPARC promotes invasion, but suppresses proliferation, suggesting that it may be a therapeutic target for invasion, but conversely, a therapy to inhibit proliferation." (PMID 22480225, 2012). "In addition, we have shown that SPARC expression decreases glioma proliferation, and in this respect SPARC expression is advantageous." (PMID 22480225, 2012). "Therefore, HSP27 inhibition is also efficient in inducing death signaling in these glioma cells, and similar to C1.1 cells (low SPARC, low pAKT) inhibition increased sensitivity to lower doses of TMZ." (PMID 22480225, 2012). "As SPARC can also increase AKT phosphorylation, and as HSP27 and AKT interact to regulate the activity of each other, we proposed that inhibition of HSP27 may be a therapeutic approach to inhibit both SPARC-induced glioma cell invasion and survival." (PMID 22480225, 2012). "In glioma, SPARC promotes invasion, but delays tumor growth." (PMID 20525313, 2010). "SPARC has also been shown to down-regulate VEGF in glioma cells." (PMID 20525313, 2010). "We therefore examined whether the SPARC-induced decrease in glioma tumor growth was also, in part, due to alterations in matrix and/or decreased vascularity, and assessed SPARC-VEGF interactions." (PMID 18350569, 2008). "Furthermore, SPARC suppressed glioma vascularity, and this was accompanied by decreased VEGF expression and secretion, which was, in part, due to reduced VEGF165 transcript abundance." (PMID 18350569, 2008).
glioma (continued). "Therefore, we believe that the SPARC-mediated glioma targeting strategy could be effective for the precise and selective accumulation of drugs in gliomas to safely pass through the BBB and effectively deliver drugs to the target region." (PMID 36945032, 2023). "However, the function of SPARC in glioma biology is not fully understood." (PMID 31062076, 2019). "We conclude that inhibition of HSP27 alone, or in combination with pAKT inhibitor IV, may be valuable therapeutic approaches to inhibit SPARC-induced glioma cell invasion and survival in SPARC-positive/PTEN-wildtype or SPARC-positive/PTEN-null tumors, respectively." (PMID 22480225, 2012). "We then determined whether SPARC alters the surviving fraction of glioma cells treated with TMZ." (PMID 22480225, 2012). "Similarly, the tumour growth of glioma cells overexpressing SPARC was delayed in vivo." (PMID 20087345, 2010). "However, as SPARC is a negative regulator of angiogenesis, we proposed that SPARC could affect overall glioma growth by affecting vascularity." (PMID 18350569, 2008). "Because SPARC is considered to be a therapeutic target for gliomas, a further understanding of its complex signaling mechanisms is important, as targeting SPARC to decrease invasion could undesirably lead to the growth of more vascular and proliferative tumors." (PMID 18350569, 2008). "In fact, SPARC functions in an autocrine/paracrine mechanism to inhibit proliferation and tumor formation of glioma cells and enhance FAK/Rho/F-actin-mediated migration and invasion, whereas IRE1 hydrolyses SPARC mRNA to induce the opposite effect." (PMID 40563622, 2025). "Through literature research, we screened out five mRNAs (SPARC, YY1, ERBB4, MAP3K2, and FZD6) that are highly expressed in glioma tumor tissues and promote glioma progression." (PMID 37554539, 2023). "GCL_TI specifically upregulates RG markers TNC, HOPX, PTPRZ1, and VIM, astrocyte markers CLU, LGALS1, as well as genes involved in migration and glioma network formation such as CD44, SPARC, and GAP43 (One peak)." (PMID 36823172, 2023). "The nanoparticles can efficiently pass through the BBB mediated by TfR and albumin-binding receptor SPARC that were overexpressed in both the BBB and glioma cells, thus achieving biomimetic delivery to glioma." (PMID 36597214, 2023). "Protein complex, containing PTN, SPARC, SPARCL1, and HSP90B, facilitates the migration of glioma cells." (PMID 36033456, 2022). "It is known that the protein complex of HSP90B with PTN, SPARC, and SPARCL1 facilitates the migration of glioma cells." (PMID 36033456, 2022). "Downregulation of SPARC by IRE1 leads to a modulation of stress fibre formation and enhances migration properties of glioma cells." (PMID 32111004, 2020). "In this study, we used glioma cell line U87MG, which exhibits the highest expression of SPARC in the cell line." (PMID 33114661, 2020). "SPARC has been demonstrated to increase p38 MAPK phosphorylation and activate the p38 MAPK/HSP27 signaling pathway, thus promoting glioma cell migration on fibronectin." (PMID 31548362, 2019). "To assess the clinical potential of our molecular findings, we first focused on glioma cell lines with high p-AKT1/ENTPD5 levels and investigated if a reduction in white matter invasion upon SPARC depletion improves survival in a pre-clinical setting." (PMID 31062076, 2019). "The overexpression of the transporters, such as SPARC, TfRs, and GLUT-1, was demonstrated in both the orthotopic and subcutaneous U87 glioma models." (PMID 29732051, 2018). "SPARC-expressing glioma cells induce AKT phosphorylation and neutralizing exogenous SPARC by antibodies abolishes the AKT phosphorylation." (PMID 28718842, 2017). "In glioma, the inhibition of HSP27 alone or in combination with a pAKT inhibitor has been described as a promising therapy approach in SPARC-induced glioma cells." (PMID 27626687, 2016).
glioma (continued). "LN443 glioma cells are highly resistant to TMZ treatment, and have high SPARC, HSP27 and pAKT expression." (PMID 22480225, 2012). "The role of slowing and terminating the tumor growth with SPARC by inhibiting the synthesis and secretion of VEGF has been reported in glioma." (PMID 20565704, 2010). "For gliomas, one such protein is secreted protein acidic and rich in cysteine (SPARC), also known as osteonectin or BM-40." (PMID 18350569, 2008). "Therefore, we hypothesized that the previously reported suppressed tumor growth in the SPARC-transfected glial tumors, which was accompanied by decreased tumor proliferation, might be accompanied by increased matrix production and inhibition of tumor vascularity." (PMID 18350569, 2008). "A previous study pointed out that SPARC could upregulate the expression of MT1-MMP in U87MG glioma cells and then affect the activation of MMP-2, thus promoting the invasion of glioma." (PMID 38388415, 2024). "It indicates SPARC to be a strong prognostic biomarker of GBM and glioma." (PMID 35571016, 2022). "SPARC is highly expressed in GBM, where it promotes the migratory and invasive behavior of glioma cells; moreover, by suppressing tumor vascularity, through the abrogation of VEGFA expression and inhibition of VEGFR2 phosphorylation, it inhibited glioma growth and VEGF-induced DNA synthesis." (PMID 35054871, 2022). "SPARC also expressed from tumor microenvironmental components, such as endothelial cells, and this non-cancer cell originated SPARC also affect to glioma." (PMID 31695779, 2019). "Glioma cell lines (U87MG, U373, and U251) showed high SPARC expression." (PMID 31695779, 2019). "Since AKT signaling is often upregulated in gliomas due to genetic alterations of PI3 K or PTEN, we investigated whether AKT1-driven ENTPD5 expression is required for glioblastoma cells to produce SPARC." (PMID 31062076, 2019). "In turn, this consequently raises the question if less invasive gliomas, e.g., pilocytic astrocytomas or ependymomas lack diffuse infiltrative growth capacities because they do not have the intrinsic ability to secrete SPARC." (PMID 31062076, 2019). "In addition, the T12/Man-BSA NPs were also colocalized with TfRs and MRs and involvement of the TfR- and SPARC-pathways in BBB penetration and glioma-targeting delivery is suggested, along with the effect of the MRs on the targeting TAM2." (PMID 29732051, 2018). "In glioma, AKT and SHC-RAF-ERK signaling are involved in the SPARC-induced invasive capacity." (PMID 28718842, 2017). "Glioma cells in vitro and in situ express various ECM components that modulate their microenvironment and promote migration, including collagens, laminins, brevican, tenascin-C and SPARC." (PMID 19712474, 2009). "We found that silencing of CTGF in the U251 cells decreased the expression and phosphorylation of FAK and the expression of SPARC, two proteins that are strongly involved in the promotion of glioma cell migration, but did not affect the phosphorylation and expression of AKT and Erk1/2." (PMID 23390502, 2013). "SPARC siRNA-transfected glioma cells failed to invade the surrounding normal brain tissue." (PMID 23935929, 2013). "We conclude that inhibition of HSP27 alone, or in combination with pAKT inhibitor IV, may be an effective therapeutic approach to inhibit SPARC-induced glioma cell invasion and survival in SPARC-positive/PTEN-wildtype and SPARC-positive/PTEN-null tumors, respectively." (PMID 22480225, 2012). "Furthermore, the lack of coimmunoprecipitation with VEGF and the lack of VEGFR1 on the glioma cells indicate that the decrease in vascularity induced by SPARC is also not because of the inhibition of VEGF-VEGFR1 autocrine signaling in glioma cells." (PMID 18350569, 2008). "Furthermore, we hypothesized that SPARC inhibition of the VEGF-VEGFR signaling in endothelial and/or glioma cells would be involved." (PMID 18350569, 2008).
glioma (continued). "A major question is whether primary gliomas have forced or non-forced SPARC expression." (PMID 22480225, 2012). "Moreover, despite the high expression of SPARC in glioma, an albumin-binding protein, the feasibility of drug-carrying HSA as a therapeutic agent against glioma has not been sufficiently studied." (PMID 33114661, 2020).
gastric cancer (69 papers, 2004 to 2025). A primary or metastatic malignant neoplasm involving the stomach. "SPARC expression in gastric cancer is significantly associated with metastasis and can be used as a useful marker in tumor prediction." (PMID 37361568, 2023). "The prognostic significance of risk score models for gastric cancer prediction can be refined by analyzing differentially expressed genes (DEGs) using SPARC." (PMID 37577749, 2023). "High expression of COL1A1, COL3A1, COL5A1, FN1, and SPARC was significantly associated with poor survival in gastric cancer patients (p < 0.05)." (PMID 35739492, 2022). "An individual SPARC polymorphism c.*1103G > A (rs1059829), allele G, significantly correlated with tumor recurrence in gastric cancer." (PMID 34209679, 2021). "High expression of SPARC is associated with disease progression and poor survival in gastric cancer." (PMID 34885041, 2021). "SPP1 rs4754 genotype interacts with SPARC SNPs, rs1054204, rs3210714, and rs3549, via epistatic mechanisms that increases the risk of the development of gastric cancer." (PMID 34209679, 2021). "A similar effect of SPARC was unveiled in gastric cancer, where SPARC overexpression was associated with fewer lung metastasis." (PMID 33466303, 2021). "GCAF-derived SPARC was significantly associated with tumour differentiation, and low expression indicated poor differentiation in gastric cancer (P = 0.003)." (PMID 31139014, 2019). "The confirmed effects and underlying mechanisms of GCAF-derived SPARC in gastric cancer remain to be demonstrated." (PMID 31139014, 2019). "Low expression of GCAF-derived SPARC was associated with decreased differentiation and reduced 5-year overall survival and was an independent predictive factor for prognosis in gastric cancer." (PMID 31139014, 2019). "Recently, the up-regulated expression of SPARC was associated with gastric cancer, esophageal cancer and CRC, and this high levels of SPARC have been shown to be associated with poor prognosis in gastric cancer." (PMID 29262657, 2017). "It was reported that gene level of SPARC in gastric cancer tissues was increased, which was associated with tumor TNM stage, lymph node metastasis and long-term survival." (PMID 29156791, 2017). "By using confocal laser scanning microscopy and specific biomarkers for CAF, TAM and vascular endothelial cells, in the study we proved that SPARC in gastric cancer tissues was mainly expressed by cancer-associated fibroblasts." (PMID 29156791, 2017). "Increased SPARC is associated to poor prognosis in pancreatic adenocarcinoma and to lymph node metastasis in gastric cancers." (PMID 24597747, 2014). "Taken together, higher SPARC expression was significantly associated with tumour progression and advanced stages of gastric cancer." (PMID 20525171, 2010). "Our work defines the mis-regulation of SPARC in gastric carcinoma and its strong association with the more advanced stages of this disease." (PMID 15558074, 2004). "SPARC in gastric cancer tissues was mainly expressed by cancer-associated fibroblasts." (PMID 29156791, 2017). "We conclude that down-regulation of SPARC may associate with the progress of gastric cancer, and the exploration aimed to regulate SPARC expression may become a meaningful approach to improve gastric cancer treatment." (PMID 22957090, 2012). "We have Collected 49 gastric cancer tissues and corresponding normal tissues through surgical procedures(Jie Yin, Guowei Chen, Si Liu, Jianxun Zhao, Yucun Liu: Expression of SPARC in human gastric cancer is associated with the clinical-pathological features, submitted)." (PMID 20525171, 2010). "SPARC has been associated with aggressive stages of gastric cancer and is correlated with poor prognosis, which suggests that the reduction of SPARC expression may have therapeutic benefit." (PMID 20525171, 2010).